BCL2 (BCL2 apoptosis regulator)
Diseases named in the same sentence as BCL2 in open-access papers (continued):
Sharing a sentence is not in itself a finding about the gene and the disease.
meningioma (14 papers, 2012 to 2024). A generally slow growing tumor attached to the dura mater. "Here, we provide evidence that NF2-deficient meningiomas express significantly higher levels of widely recognized oncogenes BCL2 and GLI1 compared to meningiomas with missense TRAF7 mutations." (PMID 36937440, 2023). "The overexpression of BCL2 is possibly associated with reduced apoptosis, invasion and migration, particularly in higher-grade meningiomas." (PMID 28340489, 2017). "Taken together, we were able to validate three new direct targets for miR-34a-3p, SMAD4, FRAT1 and BCL2, which are likely to be implicated in the deregulation of signaling pathways that are already known to be involved in meningioma genesis and progression." (PMID 28340489, 2017). "Moreover, in patients with atypical meningioma, BCL2 is found to be associated with a shorter time to recurrence." (PMID 36883085, 2023). "Meta-analysis of two studies with 195 participants showed the association between Bcl-2 expression and RFS of meningioma patients." (PMID 38758750, 2024). "Further insights from western blot analysis elucidated that miR-190a-3p overexpression strikingly reverted the inhibitory impact of hsa_circ_0004872 upregulation on Bcl2 level in meningioma cells." (PMID 38500077, 2024). "Lower levels of microRNA-34a-3p increase BCL2 expression and induce meningiomas’ growth, invasiveness, and proliferation." (PMID 36883085, 2023). "Lower levels of microRNA-34a-3p increase SMAD4 expression and induce meningiomas’ growth, invasiveness, and proliferation.BCL2 has an antiapoptotic role." (PMID 36883085, 2023). "The analysis revealed that meningiomas with NF2 gene inactivation expressed higher levels of BCL2 and GLI1 compared with tumors harboring TRAF7 missense mutations." (PMID 36937440, 2023). "Since higher-grade meningiomas showed downregulation of miR-34a-3p and other miRNAs that directly target BCL2, we propose a crucial role for BCL2 overexpression in meningiomas." (PMID 28340489, 2017). "BCL2 is a target of several miRNAs including miR-136, miR-195 and miR-497, all of which were downregulated in higher-grade meningiomas as shown in our previous study." (PMID 28340489, 2017). "We show that SMAD4, FRAT1 and BCL2 are direct targets of miR-34a-3p and that deregulation of miR-34a-3p alters proliferation and apoptosis of meningioma cells in vitro." (PMID 28340489, 2017). "Knock- down of RLIP76 decreased Bcl-2 expression and increased caspase-3 expression at both the mRNA and protein levels, implying a functional interaction between RLIP76 and the Bcl-2 and caspase-3 pathways in meningiomas." (PMID 25993541, 2015). "It has been reported that RLIP76-related Caspase-3 and Bcl-2 are overexpressed in high grade meningioma, which correlated with recurrence and prognosis in meningioma." (PMID 25993541, 2015). "Because BCL2 was first identified as a cell death regulator following cloning from B lymphocyte malignancies, we examined the expression of lymphocyte markers in both meningioma groups." (PMID 36937440, 2023). "Taken together, these results suggest that dysregulation of the Hedgehog signaling pathway and subsequent increased expression of GLI1 and BCL2 may play a role in the development of meningioma as is the case in other cancers." (PMID 36937440, 2023). "Therefore, we examined the sensitivity of malignant meningioma cells treated with gemcitabine and everolimus to the BCL-2-specific inhibitor, venetoclax, and the BCL-xL-specific inhibitors, A-1331852 and A-1155463." (PMID 35406478, 2022). "There are a few studies on the anti-apoptotic role of BCL2 in meningiomas." (PMID 28340489, 2017). "The hypothesized effects of downregulation of SMAD4 and FRAT1 on proliferation and upregulation of BCL2 on apoptosis of meningioma cells and the link to deregulation of miR-34a-3p should be explored further, also in malignant meningioma cell lines." (PMID 28340489, 2017).
meningioma (continued). "Meningiomas with complete or partial monosomy 22 showed an increased BCL2 protein level." (PMID 28340489, 2017). "The different statistical analysis shows interesting interrelations between apoptotic genes and autophagy, and a surprising involvement of GSTP1, BCL2 DAPK1, and HIC1 that deserves further consideration in meningioma." (PMID 36011000, 2022). "In meningioma cells, overexpression of miR-34a-3p resulted in decreased protein levels of SMAD4, FRAT1 and BCL2, while inhibition of miR-34a-3p led to increased levels of these proteins as confirmed by Western blotting." (PMID 28340489, 2017). "NDRG4 gene knockdown resulted in decreased expression of Bcl-2 and BcL-xL, translocation of activated BAX into the mitochondria, cytochrome c release and enhanced cleaved caspase expression in meningioma cells." (PMID 26053091, 2015). "Immunohistochemically, HPCs typically express markers such as CD34, vimentin, CD99, and Bcl-2 while being negative for S100, which helps differentiate them from other spindle cell neoplasms like schwannomas or meningiomas." (PMID 39371697, 2024). "Taken together with the high expression of BCL2 and GLI1, these results suggest that activation of Sonic Hedgehog pathway may contribute to NF2 meningioma development." (PMID 36937440, 2023). "The treatment with gemcitabine and radiation did not consistently alter the expression of Bcl-2 and Bcl-xL in malignant meningioma cells." (PMID 34765973, 2021). "Glial fibrillary acidic protein, CD99, CD34, S-100 protein, neuron specific enolase, neurofilament, cytokeratin, cytokeratin 19, and Bcl-2 were negative in MA and meningioma area." (PMID 23198201, 2012). "Similarly, the expression of CA-IX and Bcl-2 members family (regulators of apoptosis in tumor cells) including RTRAIL-R2, RTRAIL-R4, caspase-8, cFLIP, Bak, Bcl-XL, and Mcl-1 did not associate with OS or PFS of meningioma patients (p>0.05)." (PMID 38758750, 2024). "Everolimus and gemcitabine-treated malignant meningioma cells were sensitive to A-1331852 and A-1155463, but less sensitive to venetoclax, suggesting increased dependency on BCL-xL rather than BCL-2." (PMID 35406478, 2022). "In this study, the combination of everolimus and gemcitabine sensitized malignant meningioma cells to A-1331852 and A-1155463, specific inhibitors of BCL-xL, but not to venetoclax, a specific inhibitor of BCL-2, suggesting that sensitization effects were mainly dependent on the inhibition of BCL-xL." (PMID 35406478, 2022).
metastatic melanoma (14 papers, 2008 to 2024). A melanoma that has spread from its primary site to another anatomic site. "Effects caused by silencing of Bcl-2, Bcl-xL, Bcl-w, Mcl-1, or A1 were analyzed in the metastatic melanoma cell line 1205Lu." (PMID 22292048, 2012). "An enhanced expression of Bcl-xL and Bcl-2 proteins passing from primary to metastatic melanoma has also been shown by Zhang H. and colleagues." (PMID 33803452, 2021). "Each of the primary and metastatic melanoma cell lines used in our study showed unique anti-apoptotic protein (e.g., BCL2, BCL-xL and/or MCL-1) expression signature that related with their response to BH3-mimetics." (PMID 29348439, 2018). "Complicating an antisense strategy, Bcl-2 expression may also be reduced in metastatic melanoma, and other antiapoptotic Bcl-2 proteins such as Mcl-1 or Bcl-xL may substitute for Bcl-2." (PMID 19506730, 2008). "Conversely, S213F (found in a metastatic melanoma patient) displays a lower BAX TMD binding ability and a decrease in BCL2/ BAX mitochondrial localization, thereby providing a lower level of protection from cell death." (PMID 38670940, 2024). "In total, we analysed the expression of six pro-apoptotic (Bax, Bak, Smac, Procaspase-9, Apaf-1, Procaspase-3) and three antiapoptotic proteins (Bcl-2, Bcl-xL, XIAP) in metastatic melanoma samples spotted on TMAs." (PMID 32054850, 2020). "We evaluated pretreatment mRNA expression of BCL-2 family members, BCL-2, MCL-1, BCL-XL, BCL-W, BIM, and BID in tumors of patients with metastatic melanoma." (PMID 24983357, 2014). "In this study, we therefore assessed the expression of nine apoptosis regulators (Bax, Bak, Bcl-2, Bcl-xL, Smac, Procaspase-9, Apaf-1, Procaspase-3 and XIAP) in metastatic melanoma tissues by immunohistochemistry (IHC), using antibodies that passed rigorous validation." (PMID 32054850, 2020). "Unfortunately, expression of Bcl-2 was not assessed in this clinical trial; however, previous studies on metastatic melanoma specimens suggest that patients with more advanced disease have significantly lower levels of Bcl-2 expression." (PMID 18430249, 2008).
periodontitis (14 papers, 2006 to 2025). An acute or chronic inflammatory process that affects the tissues that surround and support the teeth. "The results of the immunohistochemical analysis showed an increase in the expression of BCL-2 in the animals with periodontitis and a reduction in the animals treated with the lowest dose of the compound (p < 0.05) (Figure 4III,IV)." (PMID 39456446, 2024). "It is predicted that PTGS2 and BCL2 are the most important targets of the Asarum–Angelica drug pair for regulating periodontitis, and AKT1, CASP3, BAX, RELA, etc., are also relatively important targets." (PMID 38139216, 2023). "The apoptosis of inflammatory cells plays an important role in the regression of acute inflammatory responses; BCL2 is an inhibitor of cell apoptosis, and its overexpression during periodontitis exacerbates inflammation." (PMID 38139216, 2023). "In preclinical studies, verbascoside was able to inhibit levels of Bax, Bcl-2, nuclear factor-κB, iNOS, and myeloperoxidase, showing anti-inflammatory benefits in a model of periodontitis." (PMID 35406100, 2022). "The present findings corroborate another study that found a higher number of Bcl-2 positive cells in the inflammatory infiltrate of periodontitis patients, suggesting that the Bcl-2 protein may play a role in the control of apoptosis in inflammatory cells." (PMID 24025186, 2013). "The authors hypothesize that P. gingivalis HmuY plays a role in the pathogenesis of chronic periodontitis, possibly by reducing or delaying apoptosis in T cells through a pathway involving the Bcl-2 protein." (PMID 24025186, 2013). "The results of molecular dynamics simulations suggested that the compounds were tightly bound and the complex was stable, suggesting that modulation of BCL2 may be a potential mechanism of action for the treatment of periodontitis with the Asarum–Angelica drug pair." (PMID 38139216, 2023). "The results showed that the main active ingredients of the Asarum–Angelica drug pair had a strong binding ability with BCL2, suggesting that the drug pair may promote inflammatory cell apoptosis and alleviate periodontitis inflammation by interfering with the formation of BCL2." (PMID 38139216, 2023). "Accordingly, the inhibition of Bcl-2 in individuals without periodontitis may be one of the underlying mechanisms that prevent these individuals from developing the disease." (PMID 24025186, 2013). "To further explore the role of senescent cells in periodontitis progression, we established an LIP mouse model treated with the senolytic drug ABT263, a Bcl2 inhibitor." (PMID 40801798, 2025). "In addition to this, CXB downregulates anti-apoptotic proteins such as Mcl-1 and Bcl-2, further amplifying its apoptotic effects.CXB’s ability to modulate inflammatory responses can lead to enhanced apoptosis in inflamed tissues, such as those affected by chronic periodontitis associated with OSCC." (PMID 39937256, 2025). "It was discovered through network graph analysis that targets such as PTGS2, BCL2, AKT1, and CASP3 are the main targets of the Asarum–Angelica drug pair in the treatment of periodontitis." (PMID 38139216, 2023).
periodontitis (continued). "The relevant genes that were involved in the PI3K/AKT pathway activation observed in the T2DM-related periodontitis included those that affect apoptosis (e.g., FOXO1, BCL2, and growth differentiation factor 15 [GDF15]) and cell cycle passage (e.g., CDKN1B and CCND1)." (PMID 38241313, 2024). "The present study also found decreased Bcl-2 expression in CD3+ T cells derived from subjects without periodontitis upon HmuY stimulation." (PMID 24025186, 2013). "This protein induces high levels of Bcl-2 in the mononuclear cells of individuals with periodontitis, resulting in the inhibition of apoptosis and thereafter enabling increased survival of CD3+ T cells, which prolong the chronic inflammatory condition in periodontitis." (PMID 31011284, 2019).
rhabdomyosarcoma (14 papers, 2006 to 2025). A rare aggressive malignant mesenchymal neoplasm arising from skeletal muscle. "Prior reports have implicated BCL2 as a potential target for pharmaceuticals in fusion positive rhabdomyosarcoma." (PMID 31480361, 2019). "The role of Bcl-2 as a biomarker in rhabdomyosarcoma has been the subject of several review articles and there are recent papers trying to correlate levels of Bcl-2 and sensitivity to Nab-paclitaxel in rhabdomyosarcoma and ES." (PMID 37720343, 2023). "Accordingly, treatment with STAT3 inhibitor, XZH-5, caused suppression of BCL-2, BCL-XL, and Survivin, and resulted in increased apoptosis in rhabdomyosarcoma cells." (PMID 31652776, 2019). "Chorein silencing significantly decreased the BCL-2 and increased the Bax transcript levels in ZF rhabdomyosarcoma cells." (PMID 25871399, 2015). "Furthermore, chorein silencing decreased the BCL-2 protein abundance in ZF rhabdomyosarcoma cells." (PMID 25871399, 2015).
fibrosarcoma (13 papers, 2005 to 2026). A malignant mesenchymal fibroblastic neoplasm affecting the soft tissue and bone. "Intratumoral administration of pardaxin inhibited tumor growth, possibly by downregulating Th1-type cytokine production (TNF-α and IFN-γ) and inducing apoptosis of fibrosarcomas by decreasing the Bax/Bcl-2 ratio and activating caspase-3." (PMID 23015777, 2012). "Increased apoptosis, associated with reduced expression of the Bcl-2 and Bcl-xl anti-apoptotic molecules, was seen in SLIT2 transfected fibrosarcomas and oesophageal squamous cell carcinomas." (PMID 22132142, 2011). "Our results are supported by studies from other groups demonstrating that overexpression of wildtype Bcl-2 can delay the onset of ceramide-induced ciPCD in yet other cell types, such as L929 fibrosarcoma cells." (PMID 19818125, 2009). "Cytochrome c expression showed an increased level, and Bcl-2 showed a decreased level after doxorubicin treatment in the fibrosarcoma cell line." (PMID 16001973, 2005). "Therefore, we have demonstrated that TOMM20 in fibrosarcoma induces resistance to BCL‐2 inhibitor, and immune checkpoint inhibition but is sensitive to complex I inhibitor." (PMID 39996379, 2025). "Specifically, when TOMM20 is overexpressed in MCA‐205 fibrosarcoma cells, it leads to an upregulation of three members of the apoptosis inhibitory BCL2 family of proteins: BCL‐2, BCL‐xl, and A1/Bfl1." (PMID 39996379, 2025). "As compared to WT controls, intravenously injected Bcl2-/- de-iniDCs were more efficient in controlling the growth of orthotopic TC1 NSCLC and MCA205 fibrosarcomas, indicating that BCL2 inhibition in DCs alone is sufficient to improve immunosurveillance." (PMID 37623817, 2023). "The levels of Bcl2, BAX, musculoaponeurotic fibrosarcoma (Maf), Nrf2, Keap1, and PGC1α in the hippocampus were assessed using the western blot method." (PMID 37885999, 2023). "We investigated whether such effects would also apply to orthotopic tumors, in particular MCA205 cutaneous fibrosarcomas and TC1 non-small cell lung cancers (NSCLC), which are not particular susceptible to in vitro killing by BCL2 inhibitors unless very high concentrations (≥10 μM) are used." (PMID 37623817, 2023).
Hodgkins lymphoma (13 papers, 2010 to 2025). A heterogeneous group of malignant lymphoid neoplasms of B-cell origin characterized histologically by the presence of Hodgkin and Reed-Sternberg (HRS) cells in the vast majority of cases. "Moreover, it was demonstrated that the HCV infected patients present the translocation involving the oncogene bcl–2 within their peripheral B–lymphocytes, representing a high risk of developing a non–Hodgkin lymphoma." (PMID 20945824, 2010). "Statistical analysis also led to the conclusion that these indexes can be taken into consideration as new prognostic factors in Hodgkin’s disease, and Bcl-2 is an independent factor that predicts poor prognosis." (PMID 29531548, 2017).